IL4 (interleukin 4)
Diseases named in the same sentence as IL4 in open-access papers (continued):
Sharing a sentence is not in itself a finding about the gene and the disease.
asthma (continued). "And relevant meta-analysis showed that IL-4 was significantly associated with asthma." (PMID 26000027, 2015). "Importantly, IL4 polymorphisms that associate with asthma severity and elevated IgE in individuals of European descent are more frequent in African Americans than in European Americans." (PMID 26540410, 2015). "Furthermore, our data provided the first evidence that, following gastric bypass surgery and weight loss, there was a significant reduction in these mediators including IL-4, the key TH-2 cytokine associated with asthma." (PMID 25642424, 2015). "IL-4 coordinates the Th2 immune response, which is associated with the pathophysiology of asthma." (PMID 26075216, 2015). "Excessive production of IL-4, IL-5, and IL-13 was implicated in the development of asthma." (PMID 24936861, 2014). "Over-expression of IL-4 leads to eosinophilia and mucus metaplasia as well as subepithelial fibrosis, whereas IL-5 over-expression is thought to result in an increased number of eosinophils in the airway, which is the hallmark of asthma." (PMID 24886260, 2014). "We observed up-regulated expression of IgE and IL-4 in FA-alone groups; this finding may reflect acceleration of the imbalance of Th1/Th2 cytokines and contribute to the cause and evolution of asthma." (PMID 23671638, 2013). "The increased amounts of IL-4 and IL-13 present in γc deficient mice could amplify signaling through the Type II R and enhance asthma responses." (PMID 23940740, 2013). "In addition, polymorphisms in IL-4 (related to Th2 pathway) have been associated with severity of asthma as measured by FEV1." (PMID 23573270, 2013). "In animal model, IL-4 deficient mice were shown to be protected from developing asthma." (PMID 24032029, 2013). "Airway inflammation associated with Th2 cytokines such as IL-4 and IL-13 is a principal feature of asthma, but whether these cytokines elicit expression of HLA-G is not known." (PMID 23327606, 2013). "Also the three regulatory polymorphisms in the IL-4 loci were associated with end stage renal disease, multiple sclerosis, autoimmune Grave’s disease, chronic polyarthritis, rheumatoid arthritis, asthma, rhinitis and atopic dermatitis." (PMID 23110190, 2012). "IL4 rs2243250 and rs2243274 were associated with asthma in both races (p-value <0.05)." (PMID 21387019, 2011). "However, while IL4 SNPs were associated with asthma in asthmatic children with European and African ancestry, the relative contributions of the most replicated asthma-associated SNPs varied by ancestry." (PMID 21387019, 2011). "Two SNPs in IL4 were associated with asthma in both races (p-values <0.05)." (PMID 21387019, 2011). "In addition, two IL4 promoter SNPs rs2243240 and rs2243246 discovered through imputation were also significantly associated with asthma (p-value <0.05)." (PMID 21387019, 2011). "Numerous studies have reported associations with IL-4, asthma and other allergic diseases." (PMID 21912604, 2011). "Th2 cells and their signature cytokines IL-4, IL-5, and IL-13 have key pathogenic roles in asthma." (PMID 21772663, 2011). "Significant associations of SNPs in IL4 with asthma were reported in 15 different populations." (PMID 21103062, 2010). "That study demonstrated that maternally injected monoclonal IL-4 antibody could attenuate offspring asthma susceptibility." (PMID 19252738, 2009). "NIEHS has funded research on genes associated with asthma susceptibility and has focused funding of genetic research on interleukin-4 and interleukin-13, two cytokines that, among other things, help regulate adaptive immunity to allergens and other asthma triggers." (PMID 19654926, 2009). "The data demonstrate a useful approach to assay for transplacental passage of functional maternal molecules, and indicate that molecules other than IL-4 and IL-13 may mediate transplacental effects in maternal transmission of asthma risk." (PMID 19252738, 2009).
asthma (continued). "However, IL-4 can also be considered as proinflammatory, since its expression and a Th2 type response are associated with allergies and asthma, but it is still regarded mainly as an anti-inflammatory cytokine." (PMID 19753321, 2009). "Interferon (IFN)-γ, thought to be deficient in asthma, can antagonize some of the effects of IL-4." (PMID 16472404, 2006). "However, pairwise combinations of SNPs in the IL4 gene were significantly associated with asthma and allergic sensitization, primarily in the European American sample." (PMID 16336695, 2005). "Released following airway epithelial injury, it activates the ST2 receptor, induces the production of IL-4, IL-5, and IL-13 by Th2 cells, mast cells, and other cell types, drives eosinophilic inflammation and airway hyperresponsiveness, and is closely linked to asthma susceptibility." (PMID 41561024, 2025). "Conversely, eosinophilic asthma, classified as type-2 high asthma, is commonly associated with allergic triggers and is characterized by a significant presence of eosinophils within the airways, and associated with elevated levels of cytokines, like IL-4, IL-5, IL-13, and IgE." (PMID 40512736, 2025). "Multiple studies have shown that clinical events resulting into neonatal IL-4 over-exposure, such as asthma in early life and food allergy, were associated with brain damage and that the neuroinflammation induced by them might lead to cognitive impairments, anxiety-/depressive-like behaviors." (PMID 38315435, 2024). "Hence, the efficacy of dupilumab in inhibiting the pathobiologic mechanisms underlying type 2 inflammation, strongly dependent on IL-4 and IL-13 actions, explains the extension of the therapeutic effects of this monoclonal antibody to both asthma and nasal polyposis in our patients." (PMID 37063895, 2023). "High IgE levels may also be associated to T2 high asthma, and like FeNO the T2 high-associated increased total IgE levels decreased during inhibition of alarmin IL-33, IL-13 and dual IL-4 and IL-13 signalling." (PMID 40980110, 2023). "Furthermore, TNF-α and IL-6 also have been highlighted to be responsible for the association between obesity and asthma, since they could enhance the production of IL-4 and IL-5, being both found raised in eosinophilic asthma." (PMID 37920579, 2023). "To date, asthma has been classically associated with type 2 inflammation, characterized by high levels of immunoglobin E (IgE), eosinophils, fractional exhaled nitric oxide (FeNO), and cytokines frequently found in allergic responses including interleukin 4, 5, 13 and 9 (IL-4, IL-5, IL-13, IL-9)." (PMID 35409241, 2022). "For example, it is thought an inflammatory type 2 response associated with cytokines (IL-4, IL-5, and IL-13) and the clinical inflammatory phenotype of asthma marked by eosinophilia may have protective effects through the activation of the antiviral host defence and promotion of viral clearance." (PMID 36105903, 2022). "In asthma patients, Th2 is hyperactive, causing a rise in IL4 and immunoglobulin E (IgE), which stimulates the growth and activation of eosinophilic granulocytes, which then secretes a variety of inflammatory mediators, leading to bronchial chronic inflammation and asthma." (PMID 36140412, 2022). "In fact, as is the case of T2-high and T2-low asthma, underlying immunopathophysiological mechanisms (involving cytokines) have been identified and there is even effective medication targeted at these mechanisms (e.g., anti-IgE, anti-IL-5, anti-IL-5 receptor or anti-IL4/IL3 receptor α-chain)." (PMID 34436475, 2021). "Type 2 inflammation (type 2 T helper cell lymphocyte) is common in asthma patients, and it is linked to certain inflammatory cells (mast cells, eosinophils, type 2 T helper cell lymphocyte, IgE-producing plasma cells, and basophils) and cytokine profiles (IL-13, IL-5, IL-4)." (PMID 34516405, 2021).
asthma (continued). "In addition to regulating IgE production, IL-13 and IL-4 are implicated in cardinal features of asthma, such as extravasation and trafficking of eosinophils into the tissue, goblet cell maturation, mucus secretion, bronchial hyperresponsiveness, and tissue remodeling." (PMID 33643321, 2021). "Moreover, the hyperactivity of the IL-4/STAT6 pathway is associated with asthma and chronic obstructive pulmonary disease, and the transcriptional inhibitors of this pathway are potential targets for the prevention and treatment of diseases caused by the hyperactivity of the IL-4/STAT6 pathway." (PMID 33228696, 2020). "In terms of targeting interleukin, increased expression of IL-4 is thought to be associated with IPF, and dupilumab was also effective in asthma exacerbations, implying that inhibition of IL-4 may alleviate lung damage caused by SARS-CoV-2 by attenuating inflammation." (PMID 33264345, 2020). "The best known phenotype of asthma is allergic asthma, in which these symptoms are caused by inhaled allergens such as house dust mites, animal dander, fungi, and pollens, triggering an immunological response driven by T helper type 2 (Th2) cells and their associated cytokines IL-4, IL-5, and IL-13." (PMID 32194407, 2020). "Blocking of IL-4 signaling in asthmatic dams by administration of anti-IL-4 antibodies before mating abolished the increased susceptibility of offspring from asthmatic dams to suboptimal sensitization protocol, suggesting that the maternal transfer of asthma risk to offspring is IL-4 dependent." (PMID 31507589, 2019). "Furthermore, interrogating how other cytokine combinations that are frequently associated with the asthma phenotype (e.g. IL-13, IL-4, TSLP) may reveal novel mechanisms for regulating XDH expression and uric acid production." (PMID 28863172, 2017). "Additionally, IL-4 SNPs are associated with increased asthma and AR risk." (PMID 28959799, 2017). "Accordingly, cytokines associated with suppressed function in asthma (IFN-γ and IL-10) which could be secreted by Treg cells increased in the treated compared with the untreated group, whereas cytokines associated with attack and progression of asthma (IL-4 and IL-5) decreased." (PMID 27527926, 2016). "However, mixed success with regard to anti-IL-4 and anti-IL-13 interventions in clinical trials to date confirms the need for a better understanding of the mechanisms of pathogenesis underlying the different Th2 ‘endotypes’ seen in asthma." (PMID 26362930, 2015). "The same allele has been linked to asthma susceptibility in a number of studies, mostly in Eurasian populations likely a side-effect of IL4 positive selection, acting not only over genetic and environmental factors, but also over epigenetic signatures shaped through time." (PMID 23641254, 2013). "The cytokines IL-4 and IL-13 are abundantly present in the lungs of asthmatics, and it may therefore not come as a surprise that markers expressed by M2 macrophages have been associated with asthma." (PMID 23533311, 2013). "The reduced levels of IL-4 and IL-9 in the non-T2 asthma imply diminished Th2 and Tfh cell support for IgE class-switch and allergic response." (PMID 41601686, 2026). "Type 2 inflammation contributes to the pathogenesis of asthma through the production of cytokines IL‐4, IL‐5, and IL‐13, thereby inducing characteristic features of asthma such as elevated eosinophil levels and airway hyperresponsiveness." (PMID 41568067, 2026). "Asthma is mainly driven by type 2 inflammation, with IL-4, IL-5, and IL-13 inducing eosinophilia, IgE production, mucus hypersecretion, and airway remodeling." (PMID 42193381, 2026). "During rhinovirus infection, type 2 cytokines—including IL-4 and IL-13—were significantly elevated in both nasal and bronchial samples of asthma patients." (PMID 41576028, 2026). "T2-high asthma is characterized by upregulated type 2 immune pathways, specifically involving IL-4 and IL-13 gene expression." (PMID 41601686, 2026).
asthma (continued). "In contrast to the innate immunity mediated by ILC2s, Th2 cells modulate adaptive immunity that secretes copious amounts of IL‐4, IL‐5, and IL‐13 in an antigen‐dependent manner, thereby playing a pivotal role in Type 2 inflammation in asthma." (PMID 41568067, 2026). "Dupilumab attenuated the expression of both TSLP and IL-8 induced by co-stimulation with dsRNA and IL-4/IL-13 in HSAECs, suggesting its potential therapeutic benefit in virus-induced asthma exacerbations, particularly in type 2 asthma." (PMID 41576028, 2026). "Specifically, upon stimulation, these cells secrete Type 2 cytokines (IL‐4, IL‐5, IL‐9, and IL‐13) which promote Type 2 inflammatory response in the body and lead to characteristic symptoms of asthma and airway remodeling." (PMID 41568067, 2026). "In patients with asthma who have a pre-existing tendency toward allergic (Th2-skewed) inflammation, the presence of Th2 cytokines—particularly IL-4 and IL-13—amplifies the release of TSLP and IL-8 from small airway epithelial cells." (PMID 41576028, 2026). "In contrast, adult T2-high asthma remains dominated by Th2 cytokines (IL-4, IL-5, and IL-13) and eosinophilia, showing robust response to biologics and corticosteroids." (PMID 41601686, 2026). "This pattern is consistent with the emerging view that pediatric non-T2 asthma often reflects a Th1/Th17-skewed, neutrophil-predominant endotype, in contrast to the classic Th2/IL-4/IL-5/IL-13-driven phenotype that dominates many adult cohorts." (PMID 41601686, 2026). "Together, these data indicate that systemic IL-4, IL-9, and TNF-α skewing characterizes T2-high asthma overall, while non-T2 pediatric asthma is marked by elevated Th1/Th17-associated and pro-inflammatory cytokines that are largely absent in adults." (PMID 41601686, 2026). "After switching to dupilumab (IL-4/IL-13 inhibitor), both cAEs and asthma improved, with complete resolution within two months." (PMID 41393760, 2025). "A previous study reported that IL‐4, FEV1/FVC, and peak expiratory flow levels were independent risk factors for the prognosis of children with moderate to severe asthma." (PMID 37385291, 2025). "IL-4, IL-13, and IL-5 production has been demonstrated to induce clinical symptoms of asthma, including eosinophilia and airway hypersensitivity, indicating a clear role for ST2+ CXCR6+ Th2 cells in driving acute allergic disease." (PMID 41256356, 2025). "Dupilumab, a human mAb that binds to IL-4Rα, inhibits both IL-4 and IL-13 signaling and reduces asthma exacerbations, decreases oral corticosteroid (OCS) dosage, and improves lung function and symptom control in patients with asthma." (PMID 40810090, 2025). "IL-4, a key driver of Th2-type inflammation, is central to airway inflammation and remodeling in asthma." (PMID 41561940, 2025). "With the development of asthma, the excessive secretion of Th2 cytokines, such as IL‐4, IL‐5, and IL‐13, is considered the primary driver of immune dysregulation." (PMID 41280738, 2025). "Dupilumab, a human monoclonal antibody targeting for interleukin (IL)-4/13 receptor α chain, is widely applied in type 2 inflammation diseases treatment, i.e., atopic dermatitis (AD), nodular prurigo, and asthma." (PMID 39975679, 2025). "The pathogenesis of asthma is closely related to the overactivation of the Th2 cell immune response, which leads to the production of type 2 cytokines such as IL-4 and IL-5." (PMID 40430465, 2025). "Dupilumab, a humanized monoclonal antibody, selectively inhibits the inflammatory signaling pathways mediated by interleukin-4 (IL-4) and IL-13, and is widely used in clinical practice for the treatment of atopic dermatitis and asthma." (PMID 40557145, 2025). "Interleukin-4 (IL-4): IL-4 is crucial for initiating and maintaining the type 2 immune response in asthma." (PMID 40564060, 2025).
asthma (continued). "The imbalance between Th2 and Th1 lymphocytes represents a predominant etiology of asthma, leading to over-production of Th2 cytokines (IL-4, IL-5, IL-13) and a decrease in IFN-γ, driving the pathophysiological changes in asthma." (PMID 40420184, 2025). "Inhibition of CRTh2 activation has been proposed as a treatment strategy for asthma inflammation by inhibiting the release of critical cytokines, including IL-5, IL-4, IL-13, IL-33, and IL-25, and blocking eosinophil and basophil degranulation." (PMID 40283665, 2025). "Asthma is characterized by the coordinated increase in IgE production induced by IL-4 and the rise in eosinophils induced by IL-5, both releasing granular substances that drive inflammation and bronchoconstriction." (PMID 41309530, 2025). "Type 2 (T2) inflammation represents the predominant immunological pathway in asthma and is characterized by eosinophilic airway infiltration together with Th2-dependent overproduction of cytokines such as IL-4, IL-5, and IL-13." (PMID 41515904, 2025). "LCK drives T-cell receptor signaling to promote Th2 polarization and cytokine release (e.g., IL-4 and IL-13), directly exacerbating IgE-mediated allergic inflammation in diseases such as asthma and atopic dermatitis." (PMID 40649880, 2025). "Another study has shown that, compared to the control group, children with asthma have significantly higher IL-4/IFN-γ ratios detected in EBC." (PMID 40558433, 2025). "Consistent with the importance of these mediators in asthma pathophysiology, approved biologic therapies for severe asthma target IgE, IL-4, IL-5, or thymic stromal lymphopoietin." (PMID 41458996, 2025). "Long-term exposure alters immune gene expressions (e.g., forkhead box protein P3, IL-4) via DNA methylation, impairing regulatory T cells (Treg) function and contributing to airway remodeling and asthma persistence." (PMID 41450494, 2025). "IL-4 is involved in activating inflammation in type 2-high asthma and stimulates mast cells to further release IL-4, IL-5 and IL-13." (PMID 41371716, 2025). "Traditionally, VCAM-1 is known to induce eosinophil transmigration through activated endothelial cells in asthma via interaction with IL-4, which leads to increased release of granule proteins in inflamed tissues." (PMID 40786589, 2025). "Type 2high asthma, which accounts for the majority of asthma cases, is driven by Th2 cells that produce cytokines such as IL-4, IL-5, and IL-13." (PMID 41145900, 2025). "Vascular remodeling accelerated by IL-4 and IL-13 is a structural change impacting asthma and COPD pathophysiology, leading to decreased lung capacity and airflow." (PMID 40191199, 2025). "• Critical for IgG1+ B cell conversion to IgE+ plasma cells(IL-4) and driving high-affinity IgE(IL-13) in allergic responses.• Positively correlates with disease severity in asthma and food allergy." (PMID 41181158, 2025). "The WBC counts, total serum IgE levels, and IL-4 concentrations in the BALF were elevated in the asthma group and PAH-exposed groups." (PMID 41150507, 2025). "Dupilumab, a dual IL-4 and IL-13 inhibitor, was originally developed for the treatment of severe asthma, but has been repurposed for use in chronic obstructive pulmonary disease, with preliminary reports of benefit in non-CF bronchiectasis." (PMID 39929713, 2025). "Approved asthma biologic antibodies target critical points surrounding the T2 immune response including T2 cytokine signaling (IL-4, IL-5, and IL-13), downstream T2 response (IgE), and upstream T2 initiation [thymic stromal lymphopoietin (TSLP)]." (PMID 39586024, 2025). "IL-4 is one of the pivotal cytokines in the development of asthma, particularly in type 2 inflammation." (PMID 40564060, 2025). "The current biologics for severe asthma treatment include omalizumab (anti-IgE), mepolizumab and reslizumab (anti-IL-5), benralizumab (anti-IL-5 receptor), dupilumab (anti-IL-4/IL-13), and tezepelumab (anti-TSLP)." (PMID 40364184, 2025).